RN7SL258P (RNA, 7SL, cytoplasmic 258, pseudogene)
Gene: Miscellaneous RNA gene on chromosome 17 (44,409,059 to 44,409,358, reverse strand). Ensembl gene ENSG00000240589.
Homologues: Orthologues: chimpanzee Metazoa_SRP (99% identical), macaque Metazoa_SRP (93% identical). Paralogues in human: RN7SL1 (84% identical), RN7SL2 (83% identical), RN7SL3 (83% identical), RN7SL126P (81% identical), RN7SL597P (81% identical), RN7SL220P (81% identical), RN7SL122P (80% identical), RN7SL712P (80% identical), RN7SL186P (79% identical), RN7SL386P (79% identical), RN7SL732P (79% identical), RN7SL804P (79% identical), and 700 more.